HIF1A (hypoxia inducible factor 1 subunit alpha)
Diseases named in the same sentence as HIF1A in open-access papers (continued):
Sharing a sentence is not in itself a finding about the gene and the disease.
cancer (continued). "A recent paper demonstrated that the expression of ACADL was downregulated by HIF-1α under hypoxic conditions in human HCC cells, and decreased ACADL expression led to cancer progression through promoting accumulation of unsaturated fat9." (PMID 32219176, 2020). "Here, we report that inhibiting neddylation activates the hypoxia-inducible factor 1α (HIF-1α) through the PI3K-Akt pathway, which eventually regulates the EMT-activator ZEB1 (zinc finger E-box binding homeobox 1) in various cancer cell lines." (PMID 33097763, 2020). "HIF-1α has a dominant role in NSCLC via MDK expression, which promotes cancer cell progression and EMT through the Nothc2-NF-κB-Hes1 signaling axis through autocrine signaling and the migration of endothelial cells and vascuolization via a paracrine mechanism." (PMID 32847073, 2020). "Within VHL-positive cancer cell lines, HDAC4 inhibition by shRNA increases HIF-1α protein acetylation levels, while HDAC4 overexpression decreases HIF-1α acetylation levels." (PMID 33109235, 2020). "The expression of HIF-1α is regulated by multiple factors and HIF-1α highly expressed in many kinds of cancers, correlating with the proliferation, invasion and metastasis." (PMID 32312328, 2020). "EGFR activation induces translocation of PKM2 into the nucleus where, in hypoxic human cancer cells, PKM2 physically interacts with and promotes transactivation of HIF-1α." (PMID 32695675, 2020). "There are even studies indicating antagonistic regulation mechanisms, showing an upregulation of HIF1α when AMPK activity is reduced, at least in cancer cells." (PMID 32244507, 2020). "The correlation between HIF-1α and GLUT-1 in inducing cancer development suggests GLUT-1 as a potential cancer therapy." (PMID 33195038, 2020). "In total, 32 cancer related genes including CCND1, MKI67, HIF1A, CDH1, RRM2, and FOXM1 were subsequently identified through Ingenuity Pathway Analysis." (PMID 32348423, 2020). "In addition, studies suggested that HIF-1α might also regulate the invasiveness of cancer cells by altering the expression of intermediate filament (vimentin, keratin), extracellular matrix component (fibronectin), and protease (MMP2 and urokinase plasminogen activator receptor)." (PMID 32211041, 2020). "FCF has also been shown to affect HIF-1α and HER2, which are both known to play a crucial role in cancer cell survival." (PMID 32094384, 2020). "The results showed that the expression of FBX8 in adjacent normal tissues was significantly higher than that in cancer tissues, while HIF-1α, CDK4, and C-Myc showed high expression in cancer tissues." (PMID 32796813, 2020). "The induction of TET1 protein coactivates HIF1α and HIF2α to enhance their transcriptional activity independent of its enzymatic activity, which leads to EMT and cancer cell invasion." (PMID 32528872, 2020). "Consistent with a role for HIFs in cancer cell survival, UPR activation also promotes cooperation between XBP1s and HIF-1α increasing survival." (PMID 32536347, 2020). "At the transcription level, despite of being unexclusive, previous reports have shown that multiple transcription factors such as HIF1α, STAT3, SREBP, and TFEB can be closely regulated by mTORC1 in cancers." (PMID 32234750, 2020). "HIF-1α drives the expression of VEGFA, which controls cellular processes involved in cancer progression." (PMID 33081836, 2020).
cancer (continued). "Cytoplasmic YB-1 facilitates the translational activation of Snail, HIF1α and Twist, which induces EMT in cancer cells." (PMID 32973139, 2020). "Following neddylation blockade, we discovered that induction of ZEB1 was mediated by HIF-1α through the activation of the PI3K/Akt/mTOR pathway, emphasizing the role of neddylation in cancer migration." (PMID 33097763, 2020). "HIF-1α and HIF-2α are clinically correlated with advanced stages and poor survival of cancer patients." (PMID 32389123, 2020). "CDK4/6 inhibitors, which have broad potential for the treatment of cancers, including MM28, should counteract the Warburg effect, and HIF1α appears to be a potent target for antimyeloma therapy." (PMID 32709889, 2020). "Some signaling pathways, such as HIF-1α, PI3K/mTOR and PPAR-γ, also up-regulate the expression of PKM2 to promote the growth of cancer cells." (PMID 32631382, 2020). "PGC-1α is known to be influenced by several signaling pathways which modify the energy status of cancer cells such as AMPK, mTORC1, HIF-1α, and glucose transporters." (PMID 32354000, 2020). "HIF‐1α/VEGF signal pathway is considered to be an important target for inhibition of EMT and antiangiogenic therapies to treat cancer disease." (PMID 30653763, 2019). "It ameliorates cancer in colon tissue by inhibiting the expression of VEGF, VEGFR2, HIF-1α/b, FGF, IL-1β, -6, -8, COX-2, and iNOS." (PMID 30871059, 2019). "Despite a small portion of overlapping target genes, HIF-1α and HIF-2α often exert different functions at different stage of cancer development." (PMID 31735169, 2019). "This identified ATF4, FOXO1, HIF1A, MAF, MYC, and SREBP1 in FGFR-dependent cancer cells whereas ATF4 and MYC in EGFR-addicted cancer cells, which were required for the transcription of the signature genes in glycolysis or SSP." (PMID 31221965, 2019). "NOTCH1 signaling is known to promote the survival and proliferation of cancer cells, which is potentiated by hypoxia through stabilization of the active form of NOTCH1 by HIF-1α." (PMID 31319505, 2019). "A number of common and cancer type-specific driver pathways have been identified, including the TGFB, EGF, Notch, and HIF-1a pathways." (PMID 31798960, 2019). "In contrast to the well-established importance of HIF-1α as a robust suppressor of apoptosis, the functional significance of HIF-2α in anti-cancer therapy has been understudied." (PMID 31151160, 2019). "Recent findings have indicated that the hypoxia‐inducible factors HIF‐1α and HIF‐2α play critical roles in the gain of more malignant phenotypes by cancer stem cells." (PMID 30959553, 2019). "We propose that this mechanical regulation of HIF-1α by tamoxifen in an oxygen-independent manner may result in an effective reduction of cell fitness to cope with hypoxic condition in HSCs, and potentially in cancer cells as well, leading to decreasing fibrosis." (PMID 30575816, 2019). "In terms of cancer stemness, IL6/STAT3 signaling has been found to induce expression of the cancer stem cell (CSC) marker CD133 via interaction of STAT3 with NF-κB and HIF-1α in HCC." (PMID 31731457, 2019). "HIFs play a distinct role in tumorigenesis, and immunohistochemical analyses show that HIF-1α and HIF-2 α are overexpressed in the majority of human cancers." (PMID 31711497, 2019). "And RNAseq revealed that multiple genes involved in angiogenesis such as HIF1a, VEGF etc. were significantly downregulated in USP22 knockout cancer cells." (PMID 31842906, 2019). "This specific gene expression profile in hypoxic cells by either HIF-1α and/or HIF-2α can contribute differently to a malignant phenotype in cancer cells." (PMID 30642030, 2019). "Vanillin possesses anti-metastatic and anti-cancer activities and inhibits STAT3-mediated HIF-1α mRNA expression in human malignant melanoma cells." (PMID 31221957, 2019).
cancer (continued). "Understanding the molecular mechanisms involved in the dynamic regulation of the HIF-1α pathway in immune cells is of central importance to the immune cell function and could be a promising strategy in the design of treatments for human inflammatory diseases and cancer." (PMID 31681292, 2019). "Since miR-21 is increased under hypoxia in a HIF-1α dependent manner, this results suggest an potential involvement of hypoxia in CAF-derived exosome-mediated cancer progression." (PMID 30925935, 2019). "The expression of HIF-1α, MDR1 and LAPTM4B in individual cancers has been well reported and related to cancer progression and metastasis at tissue level however in isolated studies." (PMID 30746305, 2019). "KEGG pathway analysis of HIF1A target genes revealed an enrichment of MAPK signaling pathway, pathways in cancer and axon guidance (FDR ≤ 0.05)." (PMID 30808328, 2019). "Thus, resveratrol shows efficacy on cancer cells under hypoxia by modulating HIF-1α-related signaling pathways, resulting in induction of apoptosis, suppression of metastatic potential, such as migration and invasion and enhancement of drug sensitivity in many types of cancer." (PMID 30791624, 2019). "Real-time PCR analysis did not reveal any significant differences in the mRNA levels of β2M, HER2, HIF-1α, VEGF, and Bcl-2 between the cancer tissues and adjacent tissues (p > 0.05)." (PMID 30866857, 2019). "In triple-negative breast cancer cells, HIF-1α induced the expression of CD47, leading to cancer stem cell phenotype switch and cancer cell escape from phagocytosis, which was mediated by bone marrow-derived macrophages." (PMID 31540045, 2019). "Understanding the molecular mechanisms involved in the regulation of the HIF-1α pathway, in particular in immune cells, is of central importance to the immune cell function and could be a promising strategy in the design of treatments for human inflammatory diseases and cancer." (PMID 31681292, 2019). "Many cancer types, including HCC, exploit HIF-1α-mediated metabolic reprogramming independently of hypoxia." (PMID 31060333, 2019). "Other studies show that HIF1α activates EMT regulators including SIP1, ZEB1 SLUG, SNAIL or TWIST to promote of cancer cell metastasis." (PMID 31371307, 2019). "We performed a multiplex gene expression analysis using the Nanostring nCounter GX Human Cancer Reference kit for PT5 with a HR−/HER2+ subtype, which revealed high expression of HIF1A and HER2/ERBB2 (nCounts >500)." (PMID 31018595, 2019). "Previous studies have shown that the expression of HIF-1α and HIF-2α differently impact on patient prognosis and other clinicopathological characteristics in several cancers, such as human NSCLC." (PMID 30642030, 2019). "Knockdown of TLR2 or YAP in CD133− cancer cells decreased HIF-1α expression under normoxia condition, suggesting HIF-1α is downstream of TLR2 and YAP." (PMID 31558702, 2019). "Blocking HIF-1α nuclear translocation should impair HIF targets, as described in cancer cells treated with Vorinostat49." (PMID 31296894, 2019). "Quercetin is another flavonoid that regulates HIF-1α, which consequently re-sensitizes Dox to Dox resistant breast cancer MCF-7/dox cells, and 4T1 cells, cisplatin and etoposide to HCT116 cancer cells." (PMID 31245292, 2019). "Further, RASSF1A overexpression augmented HIF-1α promoter occupancy and transactivation of PDK1, HK2 and LDHA in both smooth muscle cells and cancer cells." (PMID 31086178, 2019). "The elevated expression of HIF-1α, MDR1 and LAPTM4B in peripheral blood of solid tumor patients can be a predictor of metastasis, disease progression and treatment response in these cancers." (PMID 30746305, 2019).
cancer (continued). "In summary, our study demonstrates that PD synergised with 2‐DG to enhance its anti‐cancer efficacy by inhibiting the ROS/PI3K/AKT/HIF‐1α/HK2 signalling axis, providing a potential anti‐cancer strategy." (PMID 30920152, 2019). "In summary, we found that vanillic acid inhibited HIF-1α by suppression of mTOR/p70S6K/4E-BP1 and Raf/MEK/ERK signaling pathways, subsequently inhibiting proliferation and angiogenesis of human cancer cells." (PMID 30678221, 2019). "The HIF-1α-mediated activation of the PPP provides precursors for nucleotide synthesis, which aids rapid proliferation of cancer cells under energy-limited hypoxic conditions." (PMID 31078780, 2019). "Furthermore, higher HIF-1α expression was reported to be associated with shorter patients’ survival and poor CRT response, and it was also extensively demonstrated that higher radiation doses are required to kill hypoxic cancer cells compared to their well-oxygenated counterparts." (PMID 31739546, 2019). "Cancer cells can contrast oxidative stress by the up-regulation of HIF1A and VEGF, which provides more oxygen to cancer cells." (PMID 31540249, 2019). "Immunohistochemical expression of HDAC6, hypoxia inducible factors-1α (HIF-1α), programmed death-1 ligand (PD-L1), CD44 (cancer stem cell marker), and ARID1A was analysed for 106 OCCC patients." (PMID 30787326, 2019). "Macrophages sensing S1P from dying cancer cells required a second stimulus, most likely transforming growth factor (TGF)-β to stabilize HIF-1α under normoxia." (PMID 31379883, 2019). "In renal cell carcinoma, SPHK1 activity controlled HIF-2α expression and the S1PR antagonist FTY720 attenuated both HIF-1α and HIF-2α accumulation in several human cancer cell lines." (PMID 31379883, 2019). "In summary, vitamin C inhibits TNBC metastasis independently of HIF-1α and, likely, by affecting the expression of YAP1 and SYNPO2, two genes in the Hippo pathway which regulate cell mobility and cancer metastasis." (PMID 31817810, 2019). "Therefore, inhibiting HIF-1α could be an important component of cancer therapy." (PMID 30234009, 2018). "In some cases, activated macrophages and cancer cells even exploit the same regulatory mechanisms to reach their goals, as was shown, e.g, for the switch to PKM2, stabilization of HIF-1α, or expression of BCAT1." (PMID 29502308, 2018). "A few years ago it has been shown that TRAP1 is able to support cancer growth decreasing SDH activity, this leading to HIF-1α stabilization through the increase of succinate levels." (PMID 30155439, 2018). "Similar to cancer cells, in the present study primary human fibroblasts under OR and OGR demonstrate a strong elevation of HIF1α as well as Glut1 and BNIP3L/Nix protein levels." (PMID 29402948, 2018). "As a well-known HIF-1α target gene, VEGF expression can be induced by HIF-1α in many cancers, which can enhance vascular permeability, stimulate angiogenesis, and increase local tissue oxygenation." (PMID 30315244, 2018). "And as the key downstream effectors of OPN for cancer stemness, the expression levels of BMI1 and HIF1α were increased when DNMT1 was up-regulated in CD133+/CD44+ cells with shOPN." (PMID 30064482, 2018). "The study was aimed at delivering anti-HIF-1a siRNA with the intention to knockdown the expression of HIF-1a, a key transcription factor responsible for the survival of cancer cells in hypoxic environments." (PMID 30241287, 2018). "The hypoxic environment can promote stabilization of HIF1α which leads to increased expression of SREBP1 and FASN in the cancer cell line." (PMID 29588626, 2018).
cancer (continued). "The regulation of HIF1α and PKM2 expression by mTOR highlights the importance of mTOR signaling in regulation of cancer metabolism." (PMID 29844464, 2018). "EMT can regulate the metabolic reprogramming of cancer cells by regulating the many regulatory molecules involved in EMT, including Snail, Dlx-2, HIF-1α, STAT3, TGF-β, Wnt, and Akt." (PMID 30671168, 2018). "The IDF-11774, a novel clinical candidate for cancer therapy, targets HSP70 and inhibits mitochondrial respiration, resulting in the activation of AMPK and reduction in HIF-1α accumulation." (PMID 30420612, 2018). "HIF-1α dimerizes with HIF-1β, and activates transcription of target genes that play key roles in the metabolic reprogramming of cancer cells." (PMID 29748591, 2018). "The observation that hepatic stellate cells induce upregulation of TGM2, producing high basal expression of HIF-1α, is of immense importance, suggesting a major role for TGM2 in inflammation-regulated cancer progression." (PMID 30393774, 2018). "HIF-1α and HIF-2α are broadly expressed in many human cancers, whereas little is known about HIF-3α." (PMID 30423905, 2018). "Activation of HIF-1α blocks pyruvate dehydrogenase kinase (PDK) thereby suppresses TCA activity and facilitates glycolysis in cancer cells." (PMID 30151352, 2018). "For impacting on cancer cell and tissue iron levels by means of TFR1 downregulation or dietary ID leads to increased HIF1α activity culminating in increased VEGF formation and cancer graft vascularization." (PMID 30534534, 2018). "HIF-1α regulates vascular endothelial growth factor (VEGF), the principal mediator of angiogenesis in a number of cancers, under normal physiologic conditions." (PMID 30557400, 2018). "Given that RAS induces HIF-1α expression, small molecules targeting RAS during hypoxia will be effective as therapeutic agents against cancer." (PMID 29891945, 2018). "Target genes of miR-22 so far reported include HDAC4, CDK6, SIRT1, SP1, HIF-1α and PTEN, which are involved in cancer progression." (PMID 30379969, 2018). "Intra-tumoural hypoxia leads to increased glycolytic enzyme activity in many cancer types and in response cancer cells upregulate GLUT1, under the control of HIF-1α." (PMID 29719622, 2018). "Molecular method was based on the analysis of selected genes expression related to hypoxia (HIF1A, ANGPTL4, TGFB1, VEGFA, ERBB3, CA9) or specific for inflammation in hypoxic sites (CCL2, CCL5) at various time points after CT26 cancer cells inoculation." (PMID 30412628, 2018). "It should be noted that some cancer cells, including MDA-MB-231 cells, constitutively express high levels of HIF-1α and pSTAT3 under normal oxygen conditions, although their levels of expression are significantly lower as compared to hypoxia." (PMID 30347860, 2018). "It has only been reported that LOX is regulated by HIF-1α under hypoxia and is induced by TGF-β in cancer cells, the mechanisms are still largely uncovered." (PMID 29472856, 2018). "It has been proposed that in cancer cells, OGT alters HIF-1α stability via regulation of α-ketoglutarate levels." (PMID 30125331, 2018). "In contrast, genes in neural (CDS1 and CHD4) and cancer-related (BTG1, COL6A1, PMP22 and HIF1A) pathways were increased by STAT3-KD, and their expression was reduced by STAT3 expression." (PMID 29774125, 2018). "The activation of HIF-1α following hypoxic stress also upregulates Cox-2 and leads as a result to higher levels of prostaglandin E2 (PGE2), hence promoting inflammation and cancer proliferation." (PMID 30627563, 2018). "Accordingly, the activation of several oncogenes which directly sustain cancer proliferation such as STAT3, NF-κB, and HIF1α are subjected to acetylation." (PMID 29632619, 2018). "Studies show that treatment of cancer cells with EGFR-therapeutics (e.g., erlotinib, gefitinib, and cetuximab) down-regulated the levels of HIF-1α protein." (PMID 30513863, 2018).